RNU6-733P (RNA, U6 small nuclear 733, pseudogene)
Gene: Small nuclear RNA gene on chromosome 4 (107,867,807 to 107,867,910, reverse strand). Ensembl gene ENSG00000222691.
Homologues: Orthologues: chimpanzee U6 (99% identical), macaque U6 (89% identical), guinea pig U6 (83% identical), rat U6 (79% identical), dog U6 (75% identical), rabbit U6 (73% identical), guinea pig U6 (72% identical), rabbit U6 (69% identical). Paralogues in human: RNU6-11P (86% identical), RNU6-37P (86% identical), RNU6-560P (86% identical), RNU6-1094P (85% identical), RNU6-1309P (85% identical), RNU6-144P (85% identical), RNU6-21P (85% identical), RNU6-774P (85% identical), RNU6-1 (84% identical), RNU6-2 (84% identical), RNU6-24P (84% identical), RNU6-30P (84% identical), and 1289 more.